RUNX1 (RUNX family transcription factor 1)
Diseases named in the same sentence as RUNX1 in open-access papers (continued):
Sharing a sentence is not in itself a finding about the gene and the disease.
leukemia (continued). "Interference with components of these circuits can perturb RUNX1-controlled coding and non-coding transcriptional programs in leukemia." (PMID 23344057, 2013). "Both coding and miRNA genes transcriptionally controlled by RUNX1 are frequently deregulated in leukemia due to perturbation of RUNX1 function." (PMID 23344057, 2013). "RUNX1-ETO is thought to promote leukemia development through the aberrant regulation of RUNX1 (AML1) target genes." (PMID 24130502, 2013). "Our “in vitro” transduction protocol of Tal-1−/− and Runx1−/− differentiating ESCs could also be used to detect differences in the activities of mutated forms of these genes that are found in acute leukemia, therapy-derived leukemia, myelodysplastic syndrome, and chronic myelomonocytic leukemia." (PMID 23922928, 2013). "RUNX1-ETO proteins then reprogram the transcriptional landscape of the cell and cooperate with further mutations to induce leukemia development." (PMID 24130502, 2013). "One such example is RUNX1-ETO itself, which induces a significant increase in hematopoietic self-renewal yet requires cooperating mutations to induce leukemia in vivo." (PMID 24130502, 2013). "With the exception of E2A-PBX1 leukemias, RUNX1 is significantly overexpressed in MLLr leukemias compared to other ALL subtypes." (PMID 23352661, 2013). "One recent example mapped the locations of the RUNX1/ETO fusion protein, which is a leukaemia-initiating transcription factor that interferes with RUNX1 function." (PMID 24278696, 2012). "To investigate the role of RUNX1 in leukemias we compared RUNX1 expression for nine different leukemias and healthy controls in more than 2000 leukemia and control specimens derived from the MILE study." (PMID 22720055, 2012). "PRMT1 has been reported to directly methylate RUNX1, a critical transcription factor involved in approximately 30 % of pediatric leukemia cases." (PMID 22839530, 2012). "RUNX1 (also known as AML1) is involved in the development of normal hematopoiesis as well as leukemia." (PMID 22851337, 2012). "RUNX1 mutations are found in approximately 5–6% of de novo AML patients, but the mutation frequency is reportedly quite high in certain leukemia subtypes." (PMID 22145044, 2011). "One circuit involves the master transcription factor Runx1 or Acute Myeloid Leukemia 1 (AML1), miR-10a and the p63 (TP73L), three genes found implicated in leukemia." (PMID 20731828, 2010). "In humans, the CBF complex containing RUNX1 as the α-subunit is one of the most frequent targets of chromosomal and genetic alterations in leukemia." (PMID 18671852, 2008). "RUNX1 is thought to be involved in the balance between cell proliferation and differentiation, whose disruption leads to leukemia development." (PMID 18671852, 2008). "This work is the first large-scale study attempting to identify the genetic networks regulated by RUNX1, a master regulator in the development of the hematopoietic system and leukemia." (PMID 18671852, 2008). "The identification of the biological pathways regulated by RUNX1 is also of importance to shed light on its in vivo function and role in leukemia development." (PMID 18671852, 2008). "We then searched for the biological pathways associated with genes differentially expressed in TEL/AML1-positive leukemia (ETV6/RUNX1)." (PMID 17956600, 2007). "The acute myeloid leukaemia gene 1 (RUNX1/AML1/CBFA2) is one of the most frequent targets for chromosomal translocations in leukaemia." (PMID 14970850, 2004). "This work supports a model in which recruitment of PTBP1 to RUNX1 target genes promotes their efficient expression and maintains robust glycolytic output, highlighting a previously unrecognized aspect of RUNX1’s central role in leukemia pathogenesis." (PMID 41214140, 2026).
leukemia (continued). "Increased quiescence of ETV6::RUNX1+ preleukemic cells is in keeping with our previous detection of these cells in cord blood of approximately 5% of healthy newborns, offering a potential explanation for prolonged latency periods of ETV6::RUNX1+ leukemia, which can extend up to 14 years." (PMID 40177616, 2025). "Collectively, our results show that Runx1/RUNX1 loss reduces sensitivity to CHK1 inhibitors across systems: Srsf2P95H and U2AF1S34F mouse progenitors, SRSF2-mutant patient samples with RUNX1 mutation, and human leukemia lines with SRSF2 mutation (K562, KO52)." (PMID 41279606, 2025). "In addition to focal deletions, gains of chromosome arms and extra chromosomes are also recurrently observed in ETV6::RUNX1 leukemia, with an average of four copy number variations (CNVs) per case." (PMID 40634509, 2025). "Moreover, a recent study found that when only “clustered” cases of leukemia are considered (those most likely to have been initiated by an infectious agent) the frequency of the ETV6/RUNX1 translocation rises to 40%." (PMID 41497616, 2025). "Notably, ETV6::RUNX1+ BCP‐ALL showed significantly elevated H1‐0 levels compared to other leukemia entities." (PMID 40177616, 2025). "A genetic analysis of random cord blood samples found the ETV6/RUNX1 translocation in 1%, a frequency 100-fold greater than the frequency of overt leukemia with that fusion gene in the population at large, indicating that 99% of the time these expanded clones fail to develop into leukemia." (PMID 41497616, 2025). "Moreover, whole transcriptome data of 1,727 leukemia patient samples showed significantly elevated H1‐0 levels in ETV6::RUNX1+ BCP‐ALL compared to other leukemia entities." (PMID 40177616, 2025). "DNA binding by RUNX1 drives CBFβ-SMMHC–induced leukemia in mice." (PMID 40763310, 2025). "Our study identifies a dependency of RUNX1-mutant leukemias on IL-3/JAK/STAT signaling, which may enable targeting of these aggressive blood cancers with existing agents." (PMID 37581927, 2023). "Somatic RUNX1 alterations (translocations and mutations) are frequently associated with MDS and AML and are considered responsible for leukemic progression in transformation from BMF into leukemia." (PMID 37377909, 2023). "Considering RUNX1 involvement in embryonic and hematopoietic development, L1-mediated abnormal RUNX1 expression may lead to leukemia and embryonic defects." (PMID 36672189, 2023). "In patients, RUNX1-mutant (RUNX1mut) leukemias are curable only by hematopoietic cell transplant." (PMID 37581927, 2023). "However, several studies have shown that normal RUNX1 expression is required for the survival of certain types of leukemia cells." (PMID 37697370, 2023). "However, the role of RUNX1 in leukemogenesis is not fully understood, and effective therapies for RUNX1-mutant leukemias remain elusive." (PMID 37581927, 2023). "Notably, most of the perturbation studies applied fusion gene-specific siRNAs for downmodulation of RUNX1/ETO suggesting that interfering with its expression will ultimately impair leukaemia propagation and hence provides a therapeutic potential." (PMID 36823395, 2023). "While certain mutations (e.g., DNMT3A, TET2, and ASXL1) are frequently observed in clonal hematopoiesis and seem to occur relatively early in leukemogenesis, others tend to emerge later during the progression of leukemia, they include mutations in FLT3, NRAS, and RUNX1." (PMID 37958832, 2023). "Results from several in vivo DS mouse models seem to indicate that RUNX1 is not the cause for the observed abnormal hematopoiesis, myeloproliferative disease or leukemia." (PMID 37670378, 2023).
leukemia (continued). "This suggests a BCR-ABL1+ precursor clone, which lacked PAX5 inactivation and RUNX1 mutation, independently gave rise to both Late-Pro leukemia at diagnosis and Early-Pro leukemia at relapse." (PMID 37337105, 2023). "For instance, the ubiquitin ligase STUB1 regulates the stability and activity of RUNX1 in leukemia; RNF38 promotes RUNX1 ubiquitination and enhances RUNX1-mediated erythroid transcriptional program inhibition; while FZR1 regulates ubiquitin-dependent degradation of RUNX1 in aplastic anemia." (PMID 36949071, 2023). "The different roles of FOXO genes in RUNX1 leukemia and FLT3-ITD leukemia highlights the mechanistic differences between the two leukemia subtypes and why treatment of both subtypes with the same drug may fail." (PMID 38007419, 2023). "We showed that the SV landscapes in ETV6::RUNX1 and classical HD leukemia are profoundly different." (PMID 37469802, 2023). "Next generation sequencing of the leukemia cells identified CSF3R and RUNX1 mutations." (PMID 35846055, 2022). "RUNX1 is essential for hematopoiesis and is involved in the development of human leukemia." (PMID 35522574, 2022). "However, established leukemia cells can be dependent on active translation for their maintenance, and AML subtypes, namely, those with RUNX1 mutations, are therapeutically sensitive to inhibition of protein synthesis." (PMID 35921412, 2022). "While key second-hit mutations in ETV6-RUNX1+ leukemia involve loss of CDKN2A and the second copy of ETV6, the fusion gene and the native RUNX1 allele are rarely lost, suggesting that the ETV6-RUNX1 - RUNX1 axis may be required for leukemic maintenance." (PMID 36411286, 2022). "Urged expression of RUNX1 inhibits HIF-1α transcriptional activity and decreased target gene expression, such as VEGF, but that of HIF-1α enhances RUNX1 transcriptional activity, confirming the role of HIF-1α and RUNX1 in angiogenesis and differentiation of leukemia cells." (PMID 36231060, 2022). "The chromosomal translocation reactivates RUNX1 and contributes to the development of leukemia." (PMID 36520265, 2022). "Although HDACs mutations occur also exceptionally rarely in children with AML, myeloid oncoproteins and leukemia-associated fusions can recruit HDACs abnormally, such as EVI1, RUNX1::RUNX1T1 (previously AML1::ETO), so as to block differentiation and maintain the leukemic phenotype of AML." (PMID 36147798, 2022). "In such a context, upregulated RUNX1 cooperates with FLT3‐ITD to induce leukaemia." (PMID 36467848, 2022). "We discovered one P variant in high-risk (not lineage-restricted) leukemia predisposition genes: RUNX1 p.Arg204Gln in an adult patient." (PMID 35739278, 2022). "Moreover, ARID1A is involved in 2 pathways including the RUNX1 pathway, which plays an important role in the development of leukemia (Pathways section)." (PMID 36035123, 2022). "However, further studies are required to elucidate the dependency on Runx1 enhancers in normal hematopoiesis and leukemia." (PMID 35140205, 2022). "Furthermore, patients with higher RUNX1 expression had significantly shorter leukaemia‐free survival (LFS) and overall survival (OS) than those with lower expression." (PMID 36467848, 2022). "Therefore, we investigated STAT5 in primary syngeneic AMLs by comparing DEK-CAN-, PML-RARα- and RUNX1-ETO-induced leukemia." (PMID 35941390, 2022). "Runt Related Transcription Factor 1 (RUNX1) and Core-Binding Factor Runt Domain Alpha Subunit 2 Translocated To 3 (CBFA2T3, ETO2, MTG16) are master regulators of hematopoiesis and are implicated in leukemia." (PMID 33743795, 2021). "Aberrantly expressed wild-type RUNX1 has been observed in several leukemias, although the mechanisms involved in promoting leukemia development are still largely unknown." (PMID 34434964, 2021).
leukemia (continued). "We have previously shown a role for ELF1 and RUNX1 in KMT2A-AFF1 leukemias." (PMID 34088716, 2021). "Notably, RUNX1 mRNA was comparable between leukemia rescue cell lines, suggesting that PKM2 decreases RUNX1 protein stability." (PMID 33473116, 2021). "Loss of Kdm5c may be involved in the leukemogenesis of ETV6/RUNX1+ ALL, but it is doubtful whether it is a main second hit driving leukemia, as in humans it has been only observed in a relapse sample." (PMID 34336858, 2021). "In MLL-fusion-induced leukemia, dysregulated wild-type RUNX1 can promote leukemia survival." (PMID 34434964, 2021). "For instance, GATA1 mutations could affect both megakaryopoiesis and erythropoiesis, whereas variants of RUNX1 and ETV6 are involved in leukemia predisposition." (PMID 34502524, 2021). "Inhibition of RUNX1 using the chemical inhibitor Ro5-3335 in MLL-AF9 leukemia cells causes cell number depletion or cell cycle arrest and suppressed leukemia development." (PMID 34434964, 2021). "Our data indicated RUNX1 facilitated proliferation to promote leukemia cell growth." (PMID 34434964, 2021). "RUNX1 mutations, including chromosomal translocations, cause abnormal cell differentiation, but the mutation alone is not sufficient to cause leukemia." (PMID 34434964, 2021). "Since CENPE is a centrosome-associated protein that contributes to cell proliferation, we questioned whether RUNX1 regulated leukemia cell growth through CENPE." (PMID 34434964, 2021). "The role played by dysregulated wild-type RUNX1 expression plays in leukemia is still largely unknown." (PMID 34434964, 2021). "Similarly, cohesin subunits are found in conserved regulatory elements (CRE)/promoter of Runx1 in the human leukemia K562 cell line." (PMID 33928020, 2021). "Nevertheless, the underlying mechanisms of dysregulated wild-type RUNX1 in leukemia development have not been fully elucidated." (PMID 34434964, 2021). "Our results suggested that RUNX1 could induce leukemia cell growth by promoting cell proliferation, which was regulated in part by the RUNX1-CENPE axis." (PMID 34434964, 2021). "Furthermore, we demonstrated that RUNX1 knockdown in leukemia cells drastically diminished colony-forming ability." (PMID 34434964, 2021). "Leukemic fusion genes such as RUNX1/ETO constitute ideal targets for leukemia therapy." (PMID 33322186, 2020). "Mutations in DHX15 and SMC1A correlated with shorter OS in RUNX1/RUNX1T1 leukemia (DHX15: HR = 3.57, p = 0.02; SMC1A: HR = 6.47, p < 0.001), while point mutations in KIT at position D816 correlated with reduced RFS in RUNX1/RUNX1T1 leukemia (HR = 2.27, p = 0.046)." (PMID 31896782, 2020). "The disrupted products of the fusion between the ETV6 and RUNX1 transcription factors, involved in B cell maturation, could result in an overall lower maturation potential of the leukemia cells." (PMID 32415257, 2020). "However, a subsequent study showed that HSPCs expressing RUNX1‐ETO and RUNX1‐ETO9a at physiological levels were unable to develop leukaemia." (PMID 34766123, 2020). "RUNX1 is essential for human definitive hematopoiesis and leukemia." (PMID 32313936, 2020). "First case of iAMP21 was described with more than 12 signals for RUNX1 per cell and confirmation in SNP array, the second had confirmed 8–9 copies of RUNX1 in leukemia clone with karyotype 47,inc/46,XX, and the third 6–9 copies of RUNX1 per cell and karyotype 46,XY,− 21,+ mar." (PMID 31456164, 2019). "Therefore, Wnt/β-catenin signaling rapidly enhances RUNX1 expression in leukemia-derived cell lines and human CD34+ hematopoietic cells, suggesting that transcriptional deregulation of translocation-prone genes occurs prior to translocation." (PMID 31817911, 2019). "A recent study reported that PITHD1 is downregulated in leukemia and may regulate RUNX1 expression that promotes megakaryocyte differentiation, and activates the internal ribosomal entry site." (PMID 31533654, 2019).
leukemia (continued). "Finally, we also observed that mRNA and proteins that were differentially expressed between hyperdiploid and ETV6/RUNX1-positive leukemia had higher mRNA-protein correlations." (PMID 30944321, 2019). "Similarly, PMA-induced monocytic differentiation of U937 cells, a human leukemia monocyte cell line, was also attenuated by the combined expression of RUNX1-R135T with ASXL1-R693X compared to single mutant." (PMID 31640815, 2019). "Data presented here showed that either ASXL1-R693X or RUNX1-R135T mutant alone did not have much effect on leukemia cells; however, cooperative mutations led to the enhancement of HIF-1α recruitments to the promoter region of the ID1 gene." (PMID 31640815, 2019). "RUNX1 is one of the most frequently mutated genes in a variety of haematological malignancies and has been proposed to play tumour suppressor roles in leukaemia; however, more recent studies suggest that wild-type RUNX1 is required for the growth and survival of certain types of leukaemia cells." (PMID 31370857, 2019). "Similarly, loss of TET2 in the presence of RUNX1-ETO showed a genome-wide increase in DNA methylation at active enhancer regions and promotes leukemia in mouse transplantation models." (PMID 30654457, 2019). "We found that a significantly higher proportion of the genes that were differentially expressed between high hyperdiploid and ETV6/RUNX1-positive leukemias were anchor genes in both the oligo(dT) and the RiboZero RNA-seq datasets (hypergeometric test; P = 0.0139 and P = 0.00513, respectively)." (PMID 30944321, 2019). "Our results of reduction of ID1 expression by the inhibition of HIF-1α in transformed leukemia cells supports that ID1 is controlled by HIF-1α, which might be deregulated by either ASXL1 or RUNX1 mutation or coexisted mutant of both genes." (PMID 31640815, 2019). "Knockdown of Runx1 inhibits the growth and survival of Runx1-Runx1t1 leukemia cells." (PMID 31817911, 2019). "Notably, the in vitro and the in vivo screens identified distinct groups of genes relevant for RUNX1/ETO-driven leukemia propagation, suggesting that the in vivo environment required additional gene functions for successful engraftment." (PMID 30300583, 2018). "RUNX1-ETO is a leukemia fusion protein and has been shown to increase self-renewal of HSPCs28." (PMID 30013160, 2018). "RUNX1, also a cell-type specific protein, has a mode that resembles the RUNX1 motif, one that is a variant and a third that matches SP1, a known RUNX1 co-factor in leukemia." (PMID 29684008, 2018). "Our findings suggest that chromosomal rearrangements may activate RUNX1 by perturbing its transcriptional control to contribute to AML pathogenesis, in keeping with an emerging oncogenic role of RUNX1 in leukemia." (PMID 30157851, 2018). "We tested this hypothesis by using an RNAi screen to functionally interrogate transcriptional targets of the fusion protein RUNX1/ETO for their relevance for leukemia maintenance." (PMID 30300583, 2018). "Next, we assessed the role of ASXL1-MT in RUNX1-ETO leukemia using a human cell-based assay." (PMID 30013160, 2018). "Upon forced overexpression, the WT1 protein interferes with differentiation of myeloid cell lines and cooperates with the fusion protein RUNX1/RUNX1T1 (AML1/ETO) in a rapid induction of leukemia in transgenic mice, clearly demonstrating a leukemogenic role for WT1." (PMID 29152069, 2017). "On the other hand, in a normal individual a single HSC with a RUNX1 mutation does not have a competitive advantage over normal HSCs and hence does not expand and initiate leukemia." (PMID 29326930, 2017). "IgH, TCR and ETV6/RUNX1 are leukemia-specific molecular markers in E/R-positive ALL." (PMID 28418909, 2017). "The RUNX1T1 (ETO) is first identified as a fusion partner to AML1 (RUNX1) in leukemia." (PMID 28640846, 2017). "In addition, small-molecule inhibitors of the RUNX1-CBFβ interaction reduce tumor burden in murine leukemia models." (PMID 29050333, 2017).